TLR4 (toll like receptor 4)
Diseases named in the same sentence as TLR4 in open-access papers (continued):
Sharing a sentence is not in itself a finding about the gene and the disease.
atherosclerosis (continued). "Our results indicated that C8:0 reduced body fat, improved the lipid profiles, suppressed inflammatory cytokine production, downregulated aortic TLR4, MyD88, NF-κB, TNF-α, IKKα, and IKKβ mRNA expression, and alleviated atherosclerosis in the apoE−/− mice (P < 0.05)." (PMID 31182969, 2019). "The Toll-like receptor 4 (TLR4) /nuclear factor kappa B (NF-κB) pathway has significant functions in the stress response and inflammation, and recently it has been suggested to be closely related to human atherosclerosis." (PMID 31182969, 2019). "Therefore, our present work was the first to reveal that enhancing HMGB1/TLR4 signaling induced by CUMS declined the expression of ABCA1 in aorta, leading to the development of atherosclerosis as confirmed by aortic sinus Oil Red O staining." (PMID 30881312, 2019). "LPS-treated hypercholesterolemic rabbits have increased atherosclerosis compared with controls and mice lacking TLR4 have reduced atherosclerosis and plaques with decreased amounts of lipid." (PMID 31707624, 2019). "Absence of TLR4 in mice attenuates atherosclerosis, implicating a role of TLR4 in the pathogenesis of atherosclerotic lesion formation." (PMID 27563891, 2016). "In summary, our findings indicate that TLR4 may play a pivotal role in VSMC migration, which contributes to atherosclerosis progression." (PMID 27563891, 2016). "Together, these data indicate that miR-223 up-regulation might abrogate the development of atherosclerosis by blocking TLR4 signaling through activation of the PI3K/AKT pathway, and provides a promising therapeutic avenue for the treatment of atherosclerosis." (PMID 26492242, 2015). "We hypothesized that the interference of TLR4/NF-κB can ameliorate CUMS-induced inflammation and atherosclerosis in apoE-/- mice." (PMID 25860573, 2015). "To test the hypothesis, we used a CUMS model in apoE-/- mice to investigate the effects of TLR4 small interfering RNA (siRNA) and a specific NF-κB antagonist pyrrolidine dithiocarbamate (PDTC) on stress-induced inflammation and atherosclerosis." (PMID 25860573, 2015). "Hyperglycemia markedly increased TLR-4 mRNA and protein expression in macrophages of atherosclerotic lesions and increased levels of NF-κB that promoted inflammatory cytokines (TNF-α, IL-1ß, and adhesion molecules) leading to atherosclerosis." (PMID 25826421, 2015). "Toll-like receptor 4 (TLR4) is expressed in a variety of cells, such as the endothelial cells and smooth muscle cells, and participates in the inflammatory response in atherosclerosis." (PMID 24755612, 2014). "Other pathogens studied inrelation to atherosclerosis are Bacteroidesforsynthus, where the protein A secreted by the bacterium acts through CD14and TLR2 ligations to induce atherosclerosis, whereas in the case of Streptococcus mutans it is the proteinAgI/II that acts through CD14 and TLR4." (PMID 18551190, 2008). "In addition to the lipid-lowering effects, statins also possess anti-inflammatory effects, and it was reported that the inhibitory effects of statins on TLR4/NF-κB and NLRP3 inflammasome pathways contributed to the treatment of atherosclerosis and other inflammation-driven diseases." (PMID 35078487, 2022). "Therefore, TLR4 transactivation of TGFBR might play a potential role in the infection-induced development and progression of atherosclerosis." (PMID 35122536, 2022). "Moreover, our model offer for the first time an explanation for the comparable effects of IFNα or IFNγ priming on TLR4-induced activation in vascular and immune cells, which correlates with the important roles of both IFN types in vascular inflammation and atherosclerosis progression." (PMID 31231385, 2019). "Therefore, TLR4 activation by FFA could stimulate monocyte recruitment to blood vessels and promote atherosclerosis." (PMID 29649324, 2018). "Furthermore, mice lacking either TLR4 or its downstream adapter protein MyD88 are protected against atherosclerosis." (PMID 30666212, 2018).
atherosclerosis (continued). "Our current findings indicate that TAK-242 monotherapy could disrupt TLR4 signaling to ameliorate intimal hyperplasia at week 2, but the effect was not sufficient to prevent graft atherosclerosis." (PMID 29150694, 2017). "The TLR4 Asp 299Gly SNP and CD14 -159C/T SNP, rather than either SNP separately, was found to be associated with clinically relevant atherosclerosis suggesting that the CD14 -159C/T SNP may influence heart disease only in concert with variation in other genes." (PMID 23730203, 2012). "Indeed, we have recently demonstrated that a TLR-2 blockade can inhibit cytokine, chemokine and MMP production in human atherosclerosis, while interruption of TLR-4 signalling did not have a significant impact on the production of proatherogenic mediators." (PMID 20652007, 2010). "In vivo studies in apolipoprotein E (apoE) knockout mice revealed that PCSK9 silencing could inhibit the progression of atherosclerosis by reducing vascular inflammation and limiting activation of the TLR4/NF-κB signaling pathway without changing plasma cholesterol levels." (PMID 41368357, 2025). "Additionally, it has been reported that plasma levels of circulating TLR4-responsive miRNAs including miR-31, miR-181a, miR-16, and miR-145 were decreased in CAD patients, which may suggest their involvement in the pathogenesis of atherosclerosis." (PMID 32378144, 2021). "Thus, the effects of these studies on atherosclerosis are likely to be compounded by toxic effects of higher dose LPS unrelated to TLR4 and may not be truly reflective of low-grade inflammation induced by pathologically relevant dosages of endotoxemia." (PMID 27824038, 2016). "We speculate that endothelial cells lacking TLR4 may be protected from atherosclerosis." (PMID 24690886, 2014). "Our results indicate that the activation of CD14, TLR4, and TLR2 on monocytes and macrophages by a very early form of oxidized LDL induces the secretion of pro-inflammatory cytokines such as IL-1β and IL-6, which may contribute to or exacerbate inflammatory responses during atherosclerosis." (PMID 20946675, 2010). "In a hypercholesterolaemic rabbit model of atherosclerosis, carotid artery liposomal transfection of TLR2 and TLR4 cDNA revealed that upregulation of either TLR alone did not significantly affect carotid atherosclerosis." (PMID 21526997, 2011). "Toll-like receptor 4 (TLR4), a transmembrane non-catalytic protein expressed on the cell surface, is a downstream target of HMGB1 and is involved in the induction of the inflammatory program and in the progression of SLE and atherosclerosis." (PMID 35571092, 2022). "In the current study we demonstrated that although M. oryzae does not activate TLR4 signalling (due to non-detectable levels of LPS) and stimulates only mild TLR2 signalling, this bacterium can trigger an aggressive macrophage-mediated pro-inflammatory response that may potentiate atherosclerosis." (PMID 24874661, 2014).
diabetes (284 papers, 2009 to 2026). "Chronic inflammation involving toll-like receptor 4 (TLR4) has been implicated in diabetes and neuropathy development." (PMID 41167527, 2025). "Pathological immune responses via the TLR4/MyD88/NF-κB pathway and the IL-17/IL-23 axis were also linked to liver fibrosis in diabetes." (PMID 40362271, 2025). "In contrast, the TLR4 +3725G/C and +11367G/C polymorphisms identified in the Han Chinese population with type 2 diabetes mellitus (T2DM) appear as protective factors, significantly reducing the risk of T2DM." (PMID 39459627, 2024). "Single-nucleotide polymorphisms (SNPs) in the Toll-like receptor 4 (TLR4) gene have been documented in type 2 diabetes mellitus (T2DM) and other diseases in the Saudi population." (PMID 37830554, 2023). "Evidence suggests that the TLR4 pathway plays a critical role in the association between diabetes and AD." (PMID 36656815, 2023). "The activation of TLR4 has been connected to a variety of clinical difficulties that are associated with diabetes, in addition to the internal environment of the body and the microenvironment of the brain." (PMID 36656815, 2023). "We are seeking to repurpose current diabetes drugs to target the TLR4 enzyme, which has been associated to Parkinson’s disease." (PMID 36656815, 2023). "Activation of TLR4 signaling contributes to increased production of proinflammatory mediators, and the sustained chronic inflammatory state associated with diabetes." (PMID 36361652, 2022). "DP treatment alleviated the prolonged inflammatory cell infiltration time and the increase in the TLR4 pathway and inflammatory factors caused by diabetes." (PMID 35463063, 2022). "TLR4 has been shown to regulate permeability in murine retinal endothelial cells and the loss of which reduces diabetes-induced thinning of murine retinal vasculature and retinal vascular damage, respectively." (PMID 38983565, 2022). "Increased expression of TLR2 and TLR4 has been found in patients with T2D, highlighting their associations with the pathogenesis of diabetes." (PMID 36552771, 2022). "The activation of toll-like receptors 4 (TLR-4), which leads to the over expression of inflammatory markers, such as IL-1β, is one of the diabetes-associated retinal alterations." (PMID 36091806, 2022). "Recent studies have implicated the TLR4 signaling pathway in diabetes-induced inflammation in the retina." (PMID 33875782, 2021). "Subsequently, the expression of TLR4 and NF-κB p65 was examined in mouse renal tissue since the relationship between TLR4 and the proinflammatory state in renal tissue is associated with diabetes." (PMID 31191309, 2019). "TLR4 is involved in systemic chronic diseases associated with inflammation, such as chronic kidney diseases, diabetes and metabolic syndrome." (PMID 30836660, 2019). "The results showed that deficiency of TLR4 accelerated the development of diabetes and enhanced the immune cell infiltration of islets in NOD mice." (PMID 29584630, 2018). "It has been discovered that there is an association of TLR4 rs1927911 SNP with childhood asthma and disease activity of rheumatoid arthritis and type 2 diabetes mellitus." (PMID 28912808, 2017). "Several lines of evidence have revealed that TLR activation, particularly TLR4, is linked to atherosclerosis in diabetes." (PMID 28785380, 2017). "Activation of inflammation through the TLR4 has been previously implicated in the etiology of diabetes, and carrageenan exposure leads to inflammation through interaction with the TLR4, as well as ROS." (PMID 25883986, 2015). "In conclusion, the present work implies that a chronic inflammatory state underlies diabetes-psychological stress associated vascular effects with rising role of TLR-4 and subsequent cytokine production." (PMID 25826421, 2015). "Genetic deficiency of TLR4 is associated with significant reduction of aortic plaque and lower triglyceride accumulation in the heart in early stages of diabetes." (PMID 26468333, 2015).
diabetes (continued). "As cytokines have been implicated to promote dysfunction of islets in diabetes and the overall significantly enhanced TLR4 expression in diabetic islets compared to healthy islets, the TLR4 induced cytokine signature was determined in isolated islets." (PMID 24594974, 2014). "Recent experimental studies support this concept as TLR2 or TLR4 deficiency attenuated the pro-inflammatory state generated in wild-type mice with STZ-induced diabetes." (PMID 24842252, 2014). "Taken together, our results demonstrate that the progression of insulin-deficient diabetes in NOD mice is under control of TLR4." (PMID 24086519, 2013). "Our findings demonstrate that TLR4 deficiency results in an acceleration of diabetes development and immune cell infiltration of islets in NOD mice." (PMID 24086519, 2013). "We conclude that TLR4 is involved in the progression of the insulitis process thereby controlling the development of insulin-deficient diabetes in NOD mice." (PMID 24086519, 2013). "In order to study the possible role of TLR4 in diabetes development, we generated a TLR4-deficient strain of the NOD mouse, the currently best characterized model of human type 1 diabetes and analysed diabetes progression by in vivo and in vitro approaches." (PMID 24086519, 2013). "The TLR4 defect of the C57BL/10ScN mouse was backcrossed onto the NOD background and the effect of TLR4 deficiency on diabetes development was analysed by in vivo and in vitro studies." (PMID 24086519, 2013). "The aim of our investigation was to study the consequence of TLR4 deficiency on the development of insulin-deficient diabetes in the NOD mouse." (PMID 24086519, 2013). "Mice with homozygous or heterozygous TLR4 deficiency exhibited a significant acceleration of diabetes development." (PMID 24086519, 2013). "Monitoring diabetes manifestation in TLR4-deficient NOD mice revealed an accelerated onset of overt diabetes in female animals with heterozygous and homozygous TLR4 deficiency by a mean of 59 and 48 d, respectively." (PMID 24086519, 2013). "The finding of an earlier disease onset in TLR4-deficient animals implicates a role for TLR4 as a regulator of the pathomechanisms involved in diabetes development." (PMID 24086519, 2013). "Specifically, the diabetes-associated elevation in SFA can activate Toll-Like Receptor 4 (TLR4), which has been reported to initiate inflammatory signaling and enhance NAE, but not MAG synthesis." (PMID 23144998, 2012). "In addition, TLR2 and TLR4 activation can lead to endothelial dysfunction and vascular complications associated with diabetes." (PMID 40076851, 2025). "Since we did not observe an alteration in the expression of HMGB1 and HSP70, which are damage-associated molecular patterns (DAMPs) that activate TLR4, in the adrenal glands of diabetic rats and mice, we evaluated if diabetes changes the gut bacterial composition in Swiss-Webster mice." (PMID 40496562, 2025). "This suggests that TLR4 may be a significant factor in the association between endometriosis and diabetes." (PMID 38539234, 2024). "The combination of HG conditions and oxLDL treatment, both associated with the progression of diabetes, may contribute to Schwann cell apoptosis via the hyperactivation of TLR4, leading to neuronal dysfunction in diabetic neuropathy." (PMID 38525707, 2024). "TLR4, in particular, has been implicated as a key mediator of inflammation in diabetes and may contribute to the development of diabetic complications." (PMID 39290498, 2024). "We propose that the diabetes-related inflammation and dysbiosis may underline changes in TLR4 expression." (PMID 36672637, 2023). "Moreover, TLR-4 was reported to be involved in diabetes progression and insulin deficiency and/or resistance." (PMID 36544223, 2022). "Additionally, NF-κB can be activated by tools like receptor 4 (TLR4) which is also associated with diabetes development being overexpressed in various cell types and organs in affected individuals." (PMID 34034759, 2021).
diabetes (continued). "Likewise, there is insufficient knowledge about the role of TLR4 in diabetes-associated vascular dysfunction of large arteries." (PMID 32694567, 2020). "In addition, we carried out antibody-based blockade of Il-1β and Tlr4 to validate the association of these macrophage-related molecules with diabetes-induced Lgals1 expression in the mouse retina." (PMID 29170525, 2017). "In the present study we show that presence of diabetes is associated with a general T cell attenuation characterized by reduced overall T cell, Th17, IL-21R+, Treg’s and TLR4+ T cell count, while the monocyte population shows enhanced TLR4 expression." (PMID 27095356, 2016). "The purpose of this study is to explore why type 2 diabetes mellitus (T2DM) patients are susceptible to pulmonary tuberculosis through detection of serum Toll-like receptor 4 (TLR4), an important immune-related receptor, especially in terms of content and TLR4 gene polymorphism." (PMID 27123010, 2016). "Asp299Gly polymorphism in the TLR4 gene, which impairs inflammatory responses, is associated with reduced vascular inflammation, assessed by C-reactive protein and a decreased risk for coronary artery disease and diabetes." (PMID 26030867, 2015). "Conversely, TLR4 deficiency accelerates diabetes development in NOD mice." (PMID 26124756, 2015). "The authors found that both TLR2 and TLR4 expression and activity were increased in the monocytes of patients with MetS and could contribute to an increased risk for diabetes and CVD." (PMID 25329057, 2014). "Consistent with this, both diabetic TLR2 and TLR4-deficient mouse hearts showed lower triglyceride accumulation during the early stages of diabetes, as well as restricted leukocyte infiltration and a marked decrease of NF-κB and MyD88 and phosphorylation of IRAK1." (PMID 24744784, 2014). "Furthermore, genetic analysis of patients has pointed an association between TLR4 polymorphisms, diabetes prevalence, and the severity of chronic cardiomyopathy." (PMID 24744784, 2014). "In particular, polymorphisms of TLR4 gene (NM-138554.1), and particularly the rs4986790 TLR4 polymorphism, have been associated with the risk for several CVDs and other age-related diseases (i.e., Alzheimer disease, prostate cancer, and diabetes), even if contrasting results have been reported." (PMID 25120286, 2014). "To test the hypothesis that TLR4 activity is involved in the pathogenesis of insulin-deficient diabetes, we established a NOD mouse line that selectively lacks the expression of TLR4." (PMID 24086519, 2013). "On the other hand, TLR4 can induce the production of various proinflammatory cytokines and is also involved in inflammatory responses in pancreatic islets, fat, liver and kidney tissues, all of which have been implicated in the development of diabetes and systemic lupus erythematosus." (PMID 38434138, 2024). "In addition, an imbalance in intestinal flora in patients with diabetes may cause high expression of TLR4." (PMID 35419168, 2022). "However, in our current study, by introducing the selective TLR4 defect of the C57BL/10ScN mouse onto the NOD mouse background we were able to provide conclusive evidence for the involvement of TLR4 in the progression of insulin-deficient diabetes." (PMID 24086519, 2013). "In conclusion, our study demonstrates that topical application of rTMD1 enhances corneal wound healing in diabetes by inhibiting HMGB1/TLR4/NLRP3/IL‐1β–mediated inflammation." (PMID 41503166, 2026). "High lipopolysaccharide (LPS) levels in type 2 diabetes mellitus (T2DM) patients activates the Toll-like receptor 4 (TLR4), which triggers macrophage recruitment and NF-κB signaling." (PMID 40806100, 2025). "Further studies are needed to delineate the molecular mechanisms that govern TLR4 signaling in β cells and its dualistic role in diabetes development." (PMID 40969771, 2025).